STOML2 (stomatin like 2)
Diseases named in the same sentence as STOML2 in open-access papers (continued):
Sharing a sentence is not in itself a finding about the gene and the disease.
lung adenocarcinoma (1 paper, 2016). A carcinoma that arises from the lung and is characterized by the presence of malignant glandular epithelial cells. "Of the 16 distinguishing proteins, 8 were significantly elevated in lung adenocarcinoma (COPG1, STOML2, HYOU1, PDIA4, EPRS, APEX1, LRPPRC and NANS) whereas 8 proteins were significantly decreased in lung adenocarcinoma (SPTB, SPTA1, ANK1, SLC4A1, HBG1 and HBG2)." (PMID 27799870, 2016).
lymph node metastasis (1 paper, 2017). "This current study also revealed that amplification of 9p was significantly associated with lymph node metastasis that might be driven by proto-oncogenes such as CA9, VCP, DCTN3, and STOML2." (PMID 28384287, 2017).
oesophageal cancer (1 paper, 2015). "Knockdown of STOML2 reduced the growth rate of oesophageal cancer cells in vitro and in vivo and inhibited cell attachment." (PMID 26487491, 2015).
oral cancer (1 paper, 2014). "The functional significance of VCP, STOML2, and DCTN3 in oral cancer phenotypes was evaluated by shRNA-mediated knockdown experiments using oral cancer cell line SCC-9." (PMID 25060540, 2014). "Of these four lines, only the amplicon in SCC-9 spanned all four oral cancer candidate genes defined by our analyses of oral cancer tissues (VCP, STOML2, and DCTN3)." (PMID 25060540, 2014). "Within this region, VCP, STOML2, and DCTN3 were identified as candidate oncogenes and we demonstrate that each is able to regulate oral cancer phenotypes." (PMID 25060540, 2014).
cancer (16 papers, 2014 to 2025). A tumor composed of atypical neoplastic, often pleomorphic cells that invade other tissues. "STOML2, a member of the stomatin family, is upregulated in numerous cancers and linked to tumor aggressiveness." (PMID 27799870, 2016). "STOML2 has been reported to closely related to the occurrence and progression of various tumors, and overexpression of STOML2 is associated to poor prognosis in several cancers, including CRC." (PMID 38214751, 2024). "Furthermore, proteins, such as butyrophilin subfamily 1 member A1, keratin, type I cytoskeletal 10, HECT domain E3 ubiquitin protein ligase 3, nuclear receptor binding SET domain protein 3, and stomatin-like 2, were identified and implicated in cancer progression and prognosis." (PMID 40839607, 2025). "These images demonstrated that the STOML2 protein exhibited stronger staining and a more widespread distribution in cancer tissue compared with normal tissue, suggesting an increased expression and higher protein abundance." (PMID 39991825, 2025). "The IHC staining images on the HPA was only available for STOML2, which demonstrated that the staining was stronger and had a more widespread pattern in cancer liver tissue than normal liver tissue." (PMID 39991825, 2025). "Stomatin-like protein 2 (STOML2) is located in the mitochondrial inner membrane and is highly expressed in cancer cells." (PMID 36906621, 2023). "To date, only a number of reports indicate that STOML2 contributes to tumorigenesis in cancer progression and metastasis." (PMID 34774067, 2021). "STOML2 has been shown to increase cell migration and invasion through activation of nuclear factor kappa B signaling pathway in human live cancer." (PMID 34774067, 2021). "STOML2, an inner mitochondrial membrane protein, has been demonstrated promoting cancer development in several cancers." (PMID 33446239, 2021). "Analyses of five public datasets from Gene Expression Omnibus (GEO) in various cancer types also demonstrated common elevated expression profile of STOML2, especially in CRC and related metastatic lesions in liver and lung." (PMID 34781982, 2021). "Highly expressed STOML2 has been reported in a variety of cancers, yet few have detailed its function and regulatory mechanism." (PMID 34781982, 2021). "STOML2 is also well-established as an anti-apoptotic gene in cancer cells, highlighting the importance of fusion to re-establish mitochondrial homeostasis and prevent mitophagy (autophagy of mitochondria) under stress." (PMID 34381777, 2021). "Although discovery of STOML2 overexpression in multiple cancers and a handful of tracing to regulatory mechanism were reported, systemic assessment of STMOL2 is still absent." (PMID 34781982, 2021). "STOML2, as a critical lipid raft component and a member of the stomatin superfamily, is elevated in gastric, ovarian and cervical cancers, and negatively correlates with the prognosis of patients with cancer." (PMID 38214751, 2024). "STOML2 is involved in maintaining coupled mitochondrial respiration and the formation of respiratory chain complexes and has been shown to profoundly alter the metabolic profile of cancer cells." (PMID 37582965, 2023). "Other related studies have also reported the role of STOML2 in cancer." (PMID 36906621, 2023). "So far the study of STOML2 in cancer progression is still remaining on the stage of observation." (PMID 33446239, 2021). "The upregulation of STOML2 could favor cyto-protective mitophagy via stabilizing PINK1 to facilitate cancer cell migration and invasion, relieve cellular stress, and regulate the sensitivity of HCC cells to lenvatinib." (PMID 33446239, 2021). "Hence, STOML2 downregulation could also enhance dynamic mitochondrial turnover, which could further prevent excessive mitophagy and maintain cancer cell survival." (PMID 36906621, 2023).
cancer (continued). "Based on the results of current study and evidence from other researchers, we suppose that similar effect occurs in STOML2-elevated CRC cells, through which promotes cancer cell proliferation, and is worth further evaluation." (PMID 34781982, 2021). "This study presents that STOML2 is significantly upregulated in CRC and promotes cancer cell proliferation and tumor growth through MAPK signaling pathway by interaction with PHB, which suggests STOML2 as novel, potent biomarker and therapeutic target in CRC, urging for further investigation." (PMID 34781982, 2021).
tumor (13 papers, 2014 to 2025). "There is a growing number of studies demonstrating that STOML2 is implicated in tumor progression and development." (PMID 33446239, 2021). "The immunocompetent C57BL/6 mice bearing Stoml2-overexpressing or control tumor were treated with either anti-PD-1 antibody or IgG control antibody." (PMID 38214751, 2024). "Bevacizumab treatment impressively inhibited the tumor growth rate and volume induced by STOML2-overexpression." (PMID 38214751, 2024). "Our subsequent experiments revealed that STOML2 triggers the upregulation of PD-L1 expression level and mediates the tumor immune escape indicating that STOML2 contributed to CRC progression via promoting the concurrent of angiogenesis and immunosuppression." (PMID 38214751, 2024). "Intriguingly, we revealed that STOML2 is essential for CRC tumor inflammatory microenvironment, which induces angiogenesis and facilitates tumor immune escape simultaneously both in vitro and in vivo." (PMID 38214751, 2024). "In our study, we demonstrated that the lipid raft protein STOML2 upregulates VEGFC expression to promote tumor angiogenesis, leading to the increased sensitivity to bevacizumab." (PMID 38214751, 2024). "Immunochemistry of patients’ resected tissue showed relatively high STOML2 expression in tumor and metastatic lymph nodes, in comparison with normal tissue." (PMID 34781982, 2021). "Subcutaneous implantation of MC38-STOML2-shPHB cells showed slower and smaller tumor growth, compared with STOML2-overexpressed counterpart." (PMID 34781982, 2021). "Immuno-blotting assay in twelve samples and paired tissues also confirmed higher STOML2 protein expression in tumor." (PMID 34781982, 2021). "Identical to what have been found, the expression of PINK1, Parkin, and LC3B II in HCC tissues was much higher than that in peri-tumor liver tissues, and the statistical results showed positive correlation between STOML2 and PINK1." (PMID 33446239, 2021). "STOML2 is a stomatin superfamily member whose expression has been confirmed in a wide variety of tumor tissue." (PMID 28968959, 2017). "STOML2 is a protein that plays a role in regulating mitochondrial metabolism, making it valuable to explore how to intervene in tumor cells’ energy metabolism to control tumor development." (PMID 39991825, 2025). "In addition, mice with Stoml2 overexpression showed higher ratio of the Pd-1+ on Cd8+, while mice bearing Stoml2-silenced tumor exhibited lower ratio of the Pd-1+ on Cd8+ compared to their corresponding controls." (PMID 38214751, 2024). "Intriguingly, anti-PD-1 treatment strongly prolonged the survival time and increased the tumor infiltration of Cd8+ T cells in the Stoml2-overexpressing group, while immunotherapy had a limited effect on the mice survival and moderately increased the proportion of infiltration Cd8+ T cells." (PMID 38214751, 2024). "However, the role of STOML2 in modulating CRC tumor microenvironment and progression is poorly understood." (PMID 38214751, 2024). "Interestingly, we showed that STOML2 is crucial for the CRC tumor inflammation microenvironment, which induces proliferation, angiogenesis and immunosuppression in vitro and in vivo." (PMID 38214751, 2024). "Furthermore, Ki67-positive proliferation index, microvascular density (MVD), PD-L1 expression were significantly increased in Stoml2-overexpressing tumor and reduced in the Stoml2-silenced tumor as compared to their respective counterparts." (PMID 38214751, 2024). "Furthermore, the ability of STOML2-induced tumor growth and HUVEC tube formation was also strongly reversed by the JSH-23." (PMID 38214751, 2024). "STOML2 promotes tumor progression by upregulating IL-6 to promote STAT3 pathway." (PMID 35851063, 2022). "In pathological conditions, STOML2 promotes tumor progression and cell proliferation." (PMID 35794236, 2022). "PAI-1 reverses STOML2 silencing-mediated tumor cell growth inhibition in MM." (PMID 34774067, 2021).
tumor (continued). "The data showed that the expression of STOML2 in HCC was much higher than the adjacent non-tumor liver tissues on both mRNA and protein levels, which is identical to the statistical results of evaluated analyzing the mRNA expression level of STOML2 by the GEPIA database." (PMID 33446239, 2021). "In tumor-adjacent region, distinction of STOML2 expression between tumor and normal tissue was more visible, where a legible margin could be drawn." (PMID 34781982, 2021). "Thus, the role of STOML2 in tumor progression received widespread attention." (PMID 38214751, 2024). "As with Cal-27 tumor cell lines, each candidate gene caused a significant increase in the proliferation of the candidate gene expressing cell lines compared to the empty vector control cell line (VCP: P = 1.34 × 10−4, DCTN3: P = 1.16 × 10−4, STOML2: P = 2.14 × 10−5)." (PMID 25060540, 2014). "The results demonstrated that EEF2, G3BP1, G3BP2, PRPF8, RECQL4, STOML2, and UBB exhibited significantly higher expression levels in the majority of tumor tissues, whereas METTL3 and NR2C2 showed a widespread downregulation trend." (PMID 41341921, 2025). "Specifically, the expression levels of tumor proliferation and angiogenesis protein CCND1 and VEGFC were upregulated by STOML2 overexpression." (PMID 38214751, 2024). "In comparison of tissue sections from our biobank, IF staining demonstrated low STOML2 and PHB expression in normal colon, and evident co-localization between STOML2 and PHB in CRC lesions, with clear margin at the invasive front in tumor-adjacent tissue." (PMID 34781982, 2021). "Among the A3SS loci in C33A, STOML2 (overexpressed and prognostic in CCa) and BDNF-AS (tumor-suppressive in CCa) illustrate that SRPK1-associated splice-site alterations may occur in genes relevant to CCa." (PMID 41551143, 2025). "Collectively, our findings indicate that STOML2 facilitates the recruitment of TRADD and sustains NF-κB activity to upregulate CCND1, VEGFC and PD-L1, which consequently leads to tumor proliferation, angiogenesis, immune escape and poorer clinical outcomes in human in CRC." (PMID 38214751, 2024). "Thus, results above prove that STOML2 knockdown attenuates proliferation of CRC cells in vivo, both in subcutaneous and orthotopic tumor model." (PMID 34781982, 2021). "In the present study, suppression of STOML2 reduced the expression of PAI-1 mRNA and protein, implying that STOML2 may be involved in tumor angiogenesis." (PMID 34774067, 2021). "As for STOML2-knockdown cell line MC38-shSTOML2, comparing with negative control MC38-scr, tumor growth was significantly attenuated, and Ki-67 expression was lower." (PMID 34781982, 2021). "Notably, in comparison with non-metastatic HCC tissues (n = 37), the expression of STOML2 was significantly higher (P = 0.0003) in metastatic HCC tissues (n = 11), which showed intrahepatic spreading or tumor invasion into blood vessel or bile ducts." (PMID 33446239, 2021).
adenocarcinoma (1 paper, 2016). A common cancer characterized by the presence of malignant glandular cells. "Adenocarcinoma-dependent elevations in LRPPRC were associated with similar increases in STOML2 and PDIA4, which exhibited 2- and 2.3-fold increases in adenocarcinoma relative to control tissue, respectively." (PMID 27799870, 2016).
infection (1 paper, 2018). The state of being infected such as from the introduction of a foreign agent such as serum, vaccine, antigenic substance or organism. "The total amounts of TRIMs, STOML2, CDC37, PCBPs, DDX3 and PPP1C isoforms were unchanged in AGS cells within 9 h of infection." (PMID 29581850, 2018).
STOML2 also shares sentences with these, for which no sentence is quoted: amyotrophic lateral sclerosis (1 paper); esophageal adenocarcinoma (1); liver cirrhosis (1); lung carcinoma (1); neurodegenerative disease (1); osteoarthritis (1); Parkinson disease (1); virus infection (1).